CD4 (CD4 molecule)
Diseases named in the same sentence as CD4 in open-access papers (continued):
Sharing a sentence is not in itself a finding about the gene and the disease.
neuroblastoma (continued). "On the other hand, we propose that in the absence of CD8+ T-mediated immunity, CD4 CTLs can target the HLA-E+ high-risk neuroblastoma cells in a TCR- and HLA-independent manner, which in turn would be unaffected by the PD-L1 expression status on the neuroblastoma cells." (PMID 33968044, 2021). "In another syngeneic model, the combination of an anti-CD4 mAb with an IL-21-secerting neuroblastoma (NB) cell vaccine or rIL-21 induced potent CD8+ T cell responses and cooperatively cured most mice bearing systemic NB." (PMID 25961061, 2015). "Both CD4+ and CD8+ CAR-T cells significantly increased the tumor response score with neuroblastoma stimulation (P < 2.2 × 10−16 by two-sided t-test)." (PMID 39622637, 2025). "CD3+ T-cell infiltrates in neuroblastoma lesions primarily consisted of αβ CD8+ T cells and conventional αβ CD4+ T cells (Tconv), together accounting for a median of 80% of CD3+ T cells." (PMID 40897471, 2025). "In our studies, we observed an increase in CD4+ T cells in idMMR neuroblastoma tumors; therefore, we decided to treat the tumor-bearing animals with an anti-CTLA4, which mainly depends on CD4+ T cells for its effectiveness." (PMID 36068918, 2023). "In neuroblastoma, we found that high pyroptosis neuroblastoma tends to have more CD8+ T-cell, natural killer (NK) cell, and memory CD4+ T-cell infiltration, and favorable outcomes." (PMID 35664308, 2022). "In vitro, supernatants from DCs cocultured with neuroblastoma cell lines and activated contain CCL22 and CCL19, and are chemotactic for both CD4+ and CD8+ T cells." (PMID 36923280, 2022). "In an earlier study by Zhou and co-workers, production of high amounts of MIF by neuroblastomas (NB) led to a decrease in the number and infiltration of CD8+ and CD4+ T cells, and ultimately, suppression of antitumor immunity." (PMID 35842634, 2022). "In addition, high-level of both CD4 and NKG2C/E expression was associated with prolonged survival of the high-risk neuroblastoma patients, but CD8 levels were not, further suggesting that the CD4+ NKG2C/E+ T cells or CD4 CTL conferred cytotoxicity against the neuroblastoma cells." (PMID 33968044, 2021). "The PD‐1 T‐cell checkpoint protein was detected on the surface 43% of CD4+ T cells and 77% of CD8+ T cells isolated from 9464D Nb tumors growing in p50(f/f);Lys‐Cre hosts and to a similar extent in tumor from p50(f/f) mice." (PMID 33480449, 2021). "Here we investigate the potential influence of TEVs on the efficacy of CD171-specific CAR T cells from CD4+ and CD8+ T cell subsets in preclinical neuroblastoma models and assess a potential differential involvement of neurotrophin receptors in this process." (PMID 32296437, 2020). "In neuroblastoma, presence of cytotoxic CD8+ T cells, CD4+ Th1 cells and NK cells are prognostic factors of improved survival." (PMID 32983125, 2020). "In only one other non-CD19 CAR trial, targeting neuroblastoma with GD2 CAR T cells, a correlation was described between in vivo CAR T cell persistence and the proportion of CD4+ or TCM cells in the infusion product." (PMID 28082983, 2016). "Moreover, neuroblastoma-infiltrating T cells, particularly DUSP4+ CD4 T cells and CD8 T cells, displayed active downstream TIGIT and PD-1 signaling." (PMID 38181797, 2024). "Studies have also found that treatment with anti-PDL1 and/or PD-1 antibodies in concert with anti-CD4 antibody, anti-CTLA4 mAb, anti-GD2 antibody, or a CSF-R1 inhibitor can significantly decrease tumor growth compared to monotherapy alone in neuroblastoma models in vivo." (PMID 37350973, 2023). "Our findings demonstrate that induction of MMR deficiency in neuroblastoma tumors can sensitize them to anti-CTLA4 treatment, which primarily relies on CD4+ T cells, but not anti-PD1 treatment, which mainly depends on CD8+ T cells." (PMID 36068918, 2023). "Importantly, our findings indicate that anti-CTLA4 treatment of idMMR neuroblastoma tumors can induce a robust T cell response involving CD8+ and CD4+ T cells." (PMID 36068918, 2023).
neuroblastoma (continued). "CD4 CTLs express not only the activating receptors NKG2C/E, but also the inhibitory receptor NKG2A, and these activating and inhibitory receptors NKG2C/E/A share the same ligand HLA-E expressed on neuroblastoma cells." (PMID 33968044, 2021). "Since TEVs, regardless of their derivation from NTRK1- or NTRK2-expressing cells, display obstructing effects on CD4+ CAR T cells in vitro, it should be tested whether CD8+ CAR T cells are a better suited for cell-based neuroblastoma immunotherapy." (PMID 32296437, 2020). "Furthermore, another study exhibited an increased percentage of CD4+ T cells and CD45RO+CD62L+ TCM in CAR treatment of neuroblastoma, shown to prolong the persistence of CAR T cells in clinical trials." (PMID 33322408, 2020). "Diverse immune cell populations, including myeloid derived suppressor cells (MDSCs), TAMs, Cluster of differentiation (CD4) CD4+/CD8+ T cells, natural killer (NK) cells, and regulatory T cells (Treg), infiltrate neuroblastoma tumors, and through crosstalk, contribute to immunosuppression." (PMID 32983125, 2020). "In this regard, it is noteworthy that the percentage of CD4+ T cells appeared to positively correlate with the clinical outcome in neuroblastoma patients treated with GD2-CAR specific T cells, and other protocols comprise the addition of unmodified CD4+ T cells to the infusates." (PMID 25279468, 2014). "While CAR T cell viability, expression of activation and exhaustion markers as well as their cytokine production was largely unaffected, CD4+ CAR T cell cytotoxicity was significantly reduced in the presence of neuroblastoma-derived extracellular vesicles independent of NTRK1/2 expression." (PMID 32296437, 2020). "Using a panel of model cell lines based on the neuroblastoma cell line U87-MG (long used in HIV-1 entry studies because they express no CD4 or endogenous major coreceptors), we expressed individual IFITMs at interferon-induced expression levels alongside CD4 and CXCR4 or CCR5." (PMID 29354117, 2017). "Notably, depletion of CD4+ T cells alone also increased the rate of tumor growth, but to a lesser extent, depletion of CD8+ T cells alone did not accelerate tumor growth, indicating that both CD4+ and CD8+ T cells make important contributions to slowed Nb tumor growth in p50(f/f);Lys‐Cre mice." (PMID 33480449, 2021). "MYCN-amplified neuroblastomas have also been reported to contain less CD4 + and CD8 + T cells, dendritic cells, NK cells, and macrophages compared to non-MYCN-amplified neuroblastomas." (PMID 35362827, 2022). "An unexpected finding in our results was the high percentage of double negative (for CD4 and CD8) lymphocytes within the TILs population from neuroblastoma, which suggested to us infiltration of innate lymphocytes, such as γδ T cells and NKT cells." (PMID 31398192, 2019). "SH-SY5Y is a human neuroblastoma cell line expressing N-methyl-D-aspartic acid (NMDA) receptors, CXCR4, CCR5, and but not CD4, and can binds to gp120 proteins." (PMID 28392757, 2017). "TEV priming of CD4+ CAR or control T cells significantly impaired the killing activity of these cells, regardless of neurotrophin receptor expression in the SH-SY5Y target cells, whereas the TEV priming of CD8+ CAR or control T cells did not affect neuroblastoma cell cytotoxicity." (PMID 32296437, 2020).
autoimmune hepatitis (50 papers, 2007 to 2026). Hepatitis caused by autoantibodies. "Impairment in Regulatory CD4 T cells (Treg) number and function have been implicated in autoimmune hepatitis (AIH)." (PMID 41807245, 2026). "Dysregulated CD4 T cells have been implicated in autoimmune liver disease, but their phenotypes and origin are still unclear." (PMID 39880819, 2025). "The decreased Treg cells favor disruption from the normal immunoregulatory mechanisms causing autoimmune liver disease with a proliferation of CD4+ and CD8+." (PMID 34948375, 2021). "Although dysregulated activation of effector CD4+T helpers (Th) has been associated with the pathogenic process of autoimmune hepatitis, this specific mechanism is still contradictory." (PMID 30050955, 2018). "In initial reports, CD4 T-cells were suggested as the main effector population causing liver damage in autoimmune hepatitis." (PMID 21779338, 2011). "However, the lack of data available at the single-cell level for other self-antigen-specific CD4 T cells after short peptide stimulation makes it difficult to identify genes specifically linked to hepatic autoimmunity in our dataset." (PMID 39880819, 2025). "We previously reported that ERC therapy can ameliorate a variety of immune-related disorders in vivo, including transplant rejection, ulcerative colitis, and autoimmune hepatitis, via modulating CD4+ T cells." (PMID 41049287, 2025). "Immunostaining showing low CD20+/CD3+ and CD4+/CD8+ cell ratios among infiltrating lymphocytes can help differentiate irAEs from autoimmune hepatitis or idiosyncratic drug-induced liver injury." (PMID 39935938, 2025). "In this study, we developed exosomes modified to specifically bind CD4 molecules, creating engineered exosome-associated AAV vectors carrying the Foxp3 gene for autoimmune hepatitis treatment." (PMID 40284659, 2025). "Only a few clinical studies have reported the effects of anti-TNF therapy on mitigating the PBC in patients with RA and reducing TNF-producing CD4 + T cells, serum transaminases, and immunoglobulins in patients with autoimmune hepatitis." (PMID 37784156, 2023). "Recently, our research group found that the precursor sequence miR-7b is the main source of mature miR-7 expression in CD4+T cell activation in a mouse autoimmune hepatitis model." (PMID 37627250, 2023). "IL-17RE is also highly expressed by liver resident CD4+ T cells and natural killer T cells and augments T cell function in autoimmune hepatitis together with IL-17C." (PMID 32641167, 2020). "On autoimmune hepatitis, CD4+ T cells represent the predominant population of T cells infiltrating into the liver, and Th1-like cytokines (e.g., IFN-γ and TNF-α) contribute to hepatic injury." (PMID 27679638, 2016). "α-Galcer is able to specifically activate NKT cells, producing several different types of inflammatory cells, activate CD4+ cells, and induce autoimmune hepatitis." (PMID 25977698, 2015). "In support of our findings, functional study in autoimmune hepatitis subjects revealed CD4+CD25hi+ Tregs via direct contact with target cells by modifying levels of regulatory cytokines but not by inducing target cell apoptosis." (PMID 24475019, 2014). "In human autoimmune hepatitis, CD4+ T cells predominate in mononuclear infiltration." (PMID 40092485, 2025). "Autoimmune liver diseases (AILD) involve dysregulated CD4 T cell responses against liver self-antigens, but how these autoreactive T cells relate to liver tissue pathology remains unclear." (PMID 39880819, 2025). "Inhibition of MAPK4 ameliorated the activation of CD4+ T cells in mice with autoimmune hepatitis." (PMID 36999945, 2023). "Our review suggests that autoimmune hepatitis is a rare disorder which usually develops in women about six to eight months after commencing highly active anti-retroviral treatment during the recovery of CD4 lymphocytes." (PMID 21702972, 2011).
autoimmune hepatitis (continued). "In this issue of the JCI, Kramer and colleagues used autoimmune hepatitis (AIH) as a model to explore the maintenance of autoreactive CD4+ T cells specific to O-phosphoseryl-tRNA:selenocysteine tRNA synthase (SepSecS)." (PMID 39817449, 2025). "Autoimmune hepatitis (AIH) is an immune‐mediated inflammatory disease of the liver parenchyma, characterized pathologically by CD4+ and CD8+ T lymphocyte infiltration leading to hepatocyte injury." (PMID 41394960, 2025). "Escin could protect against Con A-induced autoimmune hepatitis in mice via suppressing infiltration of neutrophils, CD4+ T cells, and monocytes into the liver, activation of Nrf2/HO-1 signaling pathway, inhibiting TNF-α/NF-κB, TNF-α/JNK, and IL-22/STAT3 signaling pathways." (PMID 36063304, 2022). "IMH inflammatory infiltrate differs from that of autoimmune hepatitis because it is predominantly composed of activated CD3+ and CD8+ T lymphocytes while CD20+ and CD4+ are characteristic of autoimmune forms." (PMID 38398187, 2024). "It has been demonstrated that the frequency of circulating CD4+CXCR5+ Tfh cells in patients with PBC is significantly higher than that in healthy controls and patients with autoimmune hepatitis." (PMID 35880178, 2022). "In patients with autoimmune hepatitis (AIH), increased frequencies of TNF-producing CD4+ T cells were detectable in peripheral blood and liver biopsy specimens compared to healthy controls." (PMID 35122118, 2022). "Most genes in the circulating CD4+ and CD19+ T lymphocytes of untreated patients with autoimmune hepatitis have been hypo-methylated, and this pattern has contrasted with the hyper-methylated pattern in PBC." (PMID 35844554, 2022). "Autoimmune hepatitis (AIH) is a severe hepatopathy mediated by aberrant activation of CD8+ and CD4+ effectors, including Th17-cells." (PMID 30941139, 2019). "Patients with autoimmune hepatitis display a mixed infiltrate of inflammatory cells in the liver, including CD8 and CD4 T-cells." (PMID 21779338, 2011). "Instead, LSEC-primed naïve CD4+ T cells acquired regulatory properties marked by suppression of naïve CD4+ responder T cell proliferation in vitro and suppression of inflammation in an ovalbumin (OVA)-specific autoimmune hepatitis model." (PMID 23965413, 2013). "As such, it is not surprising that CD4+ regulatory T cells, a key regulatory population of T cells able to curb immune responses, could be involved in both autoimmune hepatitis and chronic viral hepatitis." (PMID 26106627, 2015). "Unlike CD4+ T cells binding to liver cell MHC-II molecules to form TCR-CD3-peptide-MHC-II complexes, which are later removed from liver cells in autoimmune hepatitis, MHC-IIlo/-CD86+ DCs cannot efficiently contact CD4+ T cells." (PMID 34220808, 2021).
chlamydial infection (50 papers, 2008 to 2025). "Latterly, it was observed that B cell-deficient mice depleted of CD4+ T cells are unable to control secondary chlamydial infection in contrast to mice who were devoid of CD4+ T cells alone were able to clear the secondary infection after only a slight delay." (PMID 25386180, 2014). "Notably, combined NK cell/CD4+ T cell depletion did not result in a prolonged persisting reinfection, such as that observed in CD4-depleted antibody-deficient mice, implying that NK cells are minimally involved and ultimately dispensable for antibody-mediated immunity to Chlamydia reinfection." (PMID 28739831, 2017). "Th1 cells, a subset of CD4+ T cells that secrete type 1 cytokines, are essential for clearing Chlamydial infections by producing IFN-γ and enhancing the protective functions of immune and inflammatory cells." (PMID 39903705, 2025). "It is also possible that its reduced abundance in Endo+ women contributed to reduced CD4 T cell activity, ultimately delaying the resolution of chlamydial infection." (PMID 40793782, 2025). "This agrees with other studies showing the pivotal role of CD4-positive cells in the protective host immune response to chlamydial infections." (PMID 38240274, 2024). "While CD8+ TRM cells are key antiviral effectors, CD4+ TRM cells are likely the main contributors to defense against bacterial STIs such as chlamydia." (PMID 39203989, 2024). "We previously showed that Chlamydia trachomatis (CT)-specific systemic CD4+ IFN-γ production is an immune correlate of protection against chlamydia reinfection, which is consistent with murine chlamydia model findings." (PMID 37958786, 2023). "Opsonization of EBs with IgG enhanced viable (IncA+) chlamydial infection of dendritic cells, and enhanced in vitro proliferation of CD4+ CD8+ T cell proliferation of splenocytes from infected mice." (PMID 38441219, 2023). "Compared with infected WT control, chlamydial infection elicited increased myeloid cells and reduced lymphocyte cells in early infection, as well as increased CD4+ T cells in late infection in Fcgr1−/− mice." (PMID 36677333, 2022). "It has been reported that CCR5 expressing CD4+ T cells are critical for host protection against chlamydial infection." (PMID 33928045, 2021). "In particular, the CD4+ T cell subset has been attributed with taking up an especially important role, e.g., as a central mediator during host defense against chlamydia." (PMID 34451996, 2021). "In this study, we focused our analysis on the CD4 T-cell response that has been shown to be most crucial for protection against chlamydia—their IFN-γ response and their ability to migrate to the genital tract tissue." (PMID 32630694, 2020). "It appears that the Th1 CD4 cell response plays a dominant role in protective immunity, while Th2 CD4 cytokines (particularly IL-10) play a role in the immunopathology of chlamydial infection." (PMID 32326284, 2020). "Animal chlamydia models have demonstrated that protective immune response is mediated by CD4+ Th1 cytokine responses." (PMID 30881362, 2019). "Surprisingly, our data show that CD4+ T-cells are significantly enhanced in the genital tract TLR3-/- mice during mid-stage Chlamydial infection." (PMID 29624589, 2018). "In the experimental murine model for human intravaginal Chlamydial infections, CD4+ T-cells are required and sufficient to clear C. muridarum primary genital tract infections." (PMID 29624589, 2018). "Animal chlamydia models have demonstrated that CD4+ Th1 cytokine responses mediate protective immunity against reinfection." (PMID 30245688, 2018). "The importance in IFN-γ produced by CD4 T cells for protective immunity against chlamydial infection has been demonstrated previously for C. trachomatis and C. muridarum." (PMID 28575080, 2017). "Among T cell responses, IFN-γ secreting CD4 T cells (Th1 cells) are primary and required for clearance of chlamydial infection." (PMID 29552679, 2017).